IL6 (interleukin 6)
Diseases named in the same sentence as IL6 in open-access papers (continued):
Sharing a sentence is not in itself a finding about the gene and the disease.
Sepsis (continued). "The inflammatory cascade in sepsis is driven by the release of potent cytokines including TNF-α, interleukin (IL)-1, and IL-6, as well as other mediators like chemokines, complement, and reactive oxygen species." (PMID 37915587, 2023). "IL-6 and MPO are involved in the altered inflammatory response and they are commonly used as biomarkers for diagnosis and evaluation of severity in sepsis." (PMID 37762478, 2023). "In this study, a total of 33 putative targets were obtained by merging the SIN-targets and sepsis-related targets, and there were 3 genes with a higher degree: TNF-α, IL-6, and IL-1β." (PMID 37388447, 2023). "Our data reveal that IL-6 and MCP-1 mRNA were elevated in the cerebral cortex of sepsis survivor mice." (PMID 37175808, 2023). "Reports from as early as 1993 revealed increased IL-1β abundance in plasma from 10 newborns with clinical sepsis, in addition to increased TNF and IL-6, as compared to 22 healthy controls." (PMID 36769133, 2023). "Given the conclusions of studies into sepsis and Alzheimer’s disease, it would be beneficial to explore the methylation status of tau, ApoE, BDNF, IL-1 and IL-6 alongside more CM-specific genes such as CXCL10." (PMID 36844403, 2023). "The aim of this study was to determine the potential of procalcitonin (PCT), interleukin 6 (IL-6), interleukin 8 (IL-8) and endocan (ESM-1) to diagnose late-onset sepsis in neonates." (PMID 37755410, 2023). "In our study, EA reduced the W/D and lung tissue damage in sepsis mice, down-regulated the expression of serum inflammatory cytokines TNF-α and IL-6, and increased the survival rate of sepsis mice." (PMID 37635258, 2023). "A small set of biomarkers have been successfully used in the analytical diagnosis of sepsis, which include CRP, interleukin-6 (IL-6), and procalcitonin (PCT)." (PMID 37376129, 2023). "In our previous study, in the sepsis model induced by the cecal ligation puncture, TCE significantly reduced TNF-α, IL-1β, IL-6, TOS, OSI levels, increased TAS values, and significantly decreased caspase-3 and NF κB expression." (PMID 37476882, 2023). "The sepsis and vehicle groups had significantly higher amounts of pro-inflammatory cytokines (TNF-A, TNF-receptor, and IL-6) in both blood and renal tissue compared to the control group (p<0.05)." (PMID 36937479, 2023). "The levels of PCT and IL-6 were correlated with the recovery of sepsis, that is, the lower the levels of PCT and IL-6, the better the patients recovered after treatment, showing a negative correlation." (PMID 36694784, 2023). "The peripheral blood of patients with sepsis‐induced ALI was obtained, and the levels of inflammatory factors (interleukin‐6 [IL‐6], C‐reactive protein [CRP], and procalcitonin [PCT]) were determined." (PMID 37248197, 2023). "Inflammatory cytokines such as IL-1, IL-6, IL-18 and TNF-α are critically involved in the pathogenesis of sepsis." (PMID 37494665, 2023). "IL-6 is a key factor in the regulation of acute-phase proteins, such as CRP, and was positively correlated with CRP and sCD137 in our SIRS/sepsis cohort." (PMID 38139346, 2023). "In vivo, MAF (20 mg/kg) markedly protected the sepsis mice and reduced the serum TNF‐α and IL‐6 levels." (PMID 38455195, 2023). "Previous research has demonstrated the link between upregulated IL-6/IL6R and a poor prognosis in sepsis." (PMID 38026444, 2023). "Moreover, serum levels of cytokines TNF-α and IL-6 were decreased, and LPS-induced sepsis in mice and cynomolgus monkeys was relieved after the administration of these NPs, being promising candidates for the treatment of sepsis and cytokine-storm-related conditions." (PMID 36894763, 2023). "We observed a significant reduction in IL-1-β, IL-6, and TNF-α pro-inflammatory cytokines with betaine treatment in sepsis-induced rats, in line with the studies in the literature." (PMID 37970921, 2023). "To date, the sepsis biomarkers that commercially available in Japan are CRP, PCT, presepsin and IL-6." (PMID 37324133, 2023).
Sepsis (continued). "Platelets have shown a protective role in sepsis through the down regulation of macrophage-dependent proinflammatory cytokines (TNF-α and IL-6)." (PMID 37486928, 2023). "Statistically significant elevations in IL-6, IL1-β, TNF-α, and ANG-2 levels were found in the FIP sepsis induction group compared to the normal group." (PMID 37255096, 2023). "In patients with culture-confirmed sepsis after DOL 7, serum IL-6 has its peak on the day of a positive culture, while CRP needs 36 h to reach its peak." (PMID 36216867, 2023). "The mRNA and protein levels of IL-1β and IL-6 were significantly decreased in lung and spleen tissues from ATB1021-treated mice with sepsis compared to vehicle-treated mice." (PMID 36720915, 2023). "In this study, we demonstrated that AN69ST membrane adsorbed CVVH in critically ill patients with severe sepsis and significantly decreased inflammatory parameters, including CRP, PCT, WBC, as well as secretion of inflammatory factors including IL-6 and TNF-α." (PMID 37724124, 2023). "In our sepsis model, the serum levels of three major inflammatory cytokines, TNF-α, IL-6, and IL-1β, were drastically elevated at 12 h of induction." (PMID 36675101, 2023). "After inducing sepsis by cecal ligation and puncture (CLP), HDC-knockout mice exhibited reduced plasma histamine levels, and the increase in TNFα, IL‐1b, IL‐6 and MCP1 levels in sepsis were attenuated when there was a lack of plasma histamine." (PMID 36823620, 2023). "Since sepsis is usually accompanied by VEC dysfunction, and proinflammatory cytokines IL-1β, IL-6 and TNF-α are important in the occurrence and development of sepsis, we first examined if E2 can affect release of inflammatory cytokines from HUVEC." (PMID 37265700, 2023). "In a model of E. coli-induced sepsis, 15-epi-LXA4 presented a synergic effect with antibiotics by regulating IL-6 and TNF-α production by macrophages, thus limiting bacterial replication, neutrophil migration, and resulting in better survival rates." (PMID 37446699, 2023). "From our data, it is very obvious that both IL-6 and TNF-α levels were significantly elevated in Peli1 global knockout mice after sepsis compared to the other sepsis groups." (PMID 37296648, 2023). "A higher level of IL-6 on day 7 and a lower level of inflammation (both IL-6 and TNF-α) on day 9 were observed in the Sepsis + DEX group than in the sepsis group." (PMID 37114154, 2023). "According to the reviewed research articles, MIP-based biosensors can be applied for inflammation and sepsis biomarkers, such as human serum albumin, C-reactive protein, serum amyloid A, tumor necrosis factor-alpha (TNF-α), procalcitonin, IL-6, and IL-1β." (PMID 37366985, 2023). "In murine sepsis, RIPK1 has been shown to induce the production of GM-CSF, IL-6, IL-8, and TNF under LPS stimulation, implying that RIPK1 has a detrimental impact on sepsis." (PMID 38001795, 2023). "Despite the increased serum levels of cytokines in sepsis compared to SIRS, only serum IL-6 reached statistical significance (p < 0.001)." (PMID 36615909, 2023). "The reduced human leucocyte antigen DR molecules expression on RM enables their co-culture with PBMCs of sepsis patients which resulted in reduced ROS production, and up-regulated TGF-β while down-regulating IL6, IL8, and IL-10 in-vitro." (PMID 37696985, 2023). "This retrospective single-center study demonstrated that combining the levels and clearance of IL-6, LAC, and PCT was valuable for predicting 28-day sepsis mortality." (PMID 36383295, 2023). "The use of nanoparticles was found to facilitate the quantification of various sepsis biomarkers (CRP, IL-6, and PCT) as well as the detection of both Gram-positive and Gram-negative bacteria in whole blood samples." (PMID 37376129, 2023). "JWH-133, which also selectively activates CB2, was shown to reduce serum IL-6 and TNFα at 24 h post-induction in cecal ligation and puncture (CLP)-induced sepsis." (PMID 36555499, 2022).
Sepsis (continued). "During sepsis, the expression levels of proinflammatory cytokines, such as TNF, IL-6 and IL-1β, are increased in the central nervous system (CNS), which is believed to play a pivotal role in long-term cognitive impairment after sepsis." (PMID 35883093, 2022). "In our study, we found elevated IL-6 and TNF-α levels in the brain tissues of rats subjected to sepsis." (PMID 35949300, 2022). "The expression of iNOS, COX-2, TNF-α, IL-6, and HMGB-1 is inhibited following phlorotannin treatment in a lipopolysaccharide-induced sepsis model." (PMID 35597942, 2022). "Pro-inflammatory cytokines and inflammatory biomarkers, such as C-reactive protein (CRP), IL-1, IL-6 and TNF-α, increase after the development of sepsis." (PMID 35193654, 2022). "After cecal ligation and puncture (CLP)-induced sepsis, endoTREM-1-/- mice had restored vasorelaxation in addition to reduced serum VCAM-1 and IL-6, and prolonged 7-day survival." (PMID 35784361, 2022). "Studies have shown that XBJ mainly inhibits the activation of inflammatory pathways by inhibiting TNF-α, IL-1, IL-6, IL-8, IL-17 and PAR-1 and improves coagulation dysfunction in sepsis." (PMID 35648739, 2022). "Treatment of mice with general S1PR agonist FTY720 and S1P lyase inhibitor 4-deoxypyridoxine before inducing sepsis by peritoneal contamination and infection (PCI) reduced microvascular leakage in lung and liver, and dampened IL-6, TNFα, and MCP-1 production." (PMID 35634305, 2022). "BPF treatment indeed inhibited the CLP-induced production of IL-6, TNF-α, and CXCL1 by sepsis-induced peritoneal macrophages (consistent with the results in HUVECs and THP-1-macrophages)." (PMID 36361915, 2022). "Our previous studies indicated that serum IL-6 and TNF-α levels were significantly decreased in patients with sepsis or secondary hemophagocytic lymphohistiocytosis/macrophage activation syndrome received CRRT." (PMID 36263056, 2022). "The current findings showed that FP-induced and PCP-pretreated sepsis mice resulted in lower TNF-α, IL-6, and IL-1β contents in plasma, downregulating expression of Treg cells in the spleen." (PMID 35694296, 2022). "Zingerone also lowered the plasma levels of IL-6 and TNF-α, reduced lethality due to CLP-induced sepsis, raised lipid peroxidation, and improved the antioxidant defence system by restoring the concentrations of SOD, GPX, and CAT in kidney tissues." (PMID 36588685, 2022). "It has a higher specificity for diagnosing sepsis than procalcitonin (PCT) and IL-6, and thus has been proposed to be useful for assessing the prognosis and monitoring the course of sepsis." (PMID 35725631, 2022). "In addition, measurement of PTX3 in combination with cytokine levels (IL-6 and IL-18), and other routine clinical parameters rapidly available in ED (e.g., age, urea), can provide a promising approach for 90-days mortality prediction for sepsis patients, better than the use of a single biomarker." (PMID 36189302, 2022). "Twenty-four hours after LPS injection, mice presented characteristic symptoms of sepsis: diarrhea, malaise and piloerection, and elevated plasma TNF-α and IL-6 levels." (PMID 36330522, 2022). "We found an increase in the expression of IL-6, IL-8, IL-10, IL-18, IL-33, IP-10, MIF, MIP1a, MIP1β, MIP3a, LEPTIN, GCSF, MCSF, and ESelectin in sepsis plasma compared to w/o sepsis and HC." (PMID 35681439, 2022). "The levels of IL-6, TNF-α, and IL-1β in the control group were the lowest, and those in the sepsis group were the highest." (PMID 35186224, 2022). "In a classic Sprague‒Dawley rat model of sepsis peritonitis, resveratrol significantly decreases LPS-induced expression of NF-κB, TNF-α, IL6, IL-1β, and TLR4 and increases the expression of p-PI3K, p-AKT, and p-mTOR in the myocardium." (PMID 36483739, 2022). "We included 31 out of 204 articles evaluating the potential of IL-6 for the diagnosis of EONS in a study population of newborns with culture-proven and/or clinically suspected sepsis." (PMID 35402358, 2022).
Sepsis (continued). "LPS-mediated sepsis significantly increased inflammatory cytokines than the control group, including TNF-α, IL-6, IL-10, MCP1, as well as ROS production, in the mouse heart." (PMID 35402535, 2022). "The level of IL-6 can guide management of children with febrile neutropenia and are more specific and sensitive than CRP in the diagnosis of bacteremia/sepsis." (PMID 35463642, 2022). "The levels of IL-6, TNF-α, and IL-1β in the HECTD2siRNA group were significantly lower than those in the sepsis group (P < 0.05)." (PMID 35186224, 2022). "There was a statistically significant difference in the relative mRNA levels of IL-6 and TNF-α in the lung tissue of the sepsis group vs the sham group (P<0.05)." (PMID 36685507, 2022). "The levels of IL-6, TNF-α, and IL-1β in the miR-221 inhibitor group were significantly lower than those in the sepsis group (P < 0.05)." (PMID 35186224, 2022). "Consistent with the fact that the upregulated production and release of cytokines and chemokines contribute to sepsis and organ dysfunction, such as TNF-α, IL-6, and IL-1β, are positively related to multiple organ dysfunction syndrome (MODS) and mortality." (PMID 35184141, 2022). "Relative to sepsis controls, patients with HBD + DIC were characterized by increased expression of ferritin, IL-18, sCD163, sCD25, IL-6, and CXCL10, consistent with a biomarker signature of macrophage activation." (PMID 35190900, 2022). "Patients in the sepsis group had higher PCT, WBC, CRP, IL-1β, IL-2, IL-6, IL-8, IL-10, IL-12, IL-17, IFN-γ, and SOFA scores than those in the infection group, and the difference was statistically significant (P < 0.05)." (PMID 35937269, 2022). "Clinical studies have found that in patients with severe sepsis, the blood levels of TNF-α, IL-1β, IL-6, IL-8, IFN-γ, and MCP-1 are significantly increased." (PMID 35370629, 2022). "• Septicemia (sepsis): Myocardial ischemia produced by inflammatory mediators (tumor necrosis factor alpha (TNF-ɑ), interleukins (IL-1, IL-6), and bacterial exo- and endo-toxins." (PMID 36311415, 2022). "Baseline IL-6 at admission predicted AKI in patients with severe sepsis, and IL-6 also predicts the development of AKI and need for RRT in patients with severe sepsis." (PMID 35874763, 2022). "The correlation matrices in the sepsis group produced a single cluster showing a positive interaction among the pro-inflammatory mediators (CCL3, CCL4, IL1β, IL-6 and TNFα)." (PMID 35811678, 2022). "Splenectomy improved 28- day survival in a secondary sepsis CLP mouse model from 62% to 92%, which was concurrent with the lower release of inflammatory cytokines (IL-6, CXCL-1, and MCP-1) and a 41% increase in Tregs within 48 hours." (PMID 35281010, 2022). "Immunohistochemistry and Western blotting analysis of liver tissue also revealed that the levels of IL-6 and TNF-α protein expression were considerably greater in the sepsis group." (PMID 36685507, 2022). "IL-6 and TNF-α levels of mice at ST and IT after in vivo challenge were generally comparable to serum and plasma levels of humans with sepsis or septic shock." (PMID 35167625, 2022). "IL-6 and TNF-α represent potent proinflammatory cytokines which correlate with increased mortality and morbidity in recent studies of pediatric and adult sepsis." (PMID 36733389, 2022). "The study found that both the ACF and HJD can inhibit the release of inflammatory factors (NO, IL-1β, IL-6, and TNF-α), reduce inflammatory cell infiltration, and induce organ damage by sepsis." (PMID 36160407, 2022). "The plasma levels of TNF-α, IL-6, and IL-1β in the T2DM combined with the sepsis group were significantly higher than those in the control group (P < .001)." (PMID 35960063, 2022). "A large number of pro-inflammatory factors, such as TNF-α, IL-1β, and IL-6, and endotoxins can act on the BBB and then increase permeability in the process of sepsis." (PMID 36552192, 2022).
Sepsis (continued). "Production of proinflammatory cues including IL1, IL6, IL8, TNF, and MIP1a is a key driver of morbidity during sepsis." (PMID 35166205, 2022). "Rs12196996 GG and rs2232365 AA were also correlated with increased level of miR-23a, IL-10 and decreased level of TNF, IL-2, IFN, IL-6 and IL-1β in the peripheral blood cell samples of patients with ICU-acquired sepsis." (PMID 35156517, 2022). "Furthermore, the overexpression of miR-22 can reduce the expression of inflammatory factors (IL-1β, IL-6, and TNF-α) and NO, as well as significantly reduce cell apoptosis via PTEN/high-mobility group Box 1 (HMGB1) and TLR4/NF-κB pathway, thereby alleviating the AKI caused by sepsis." (PMID 35464083, 2022). "Similar correlations between eCIRP and biomarkers for severity, i.e., CRP, IL-6, and procalcitonin (PCT) has been observed in sepsis, community acquired pneumonia, and acute pancreatitis." (PMID 35967397, 2022). "Experimental sepsis led to a systemic cytokine storm resulting in the formation of excessive amounts of both pro-inflammatory cytokines (TNF-α, IL-1β, IL-17 and IL-6) and the anti-inflammatory cytokine IL-10." (PMID 35178052, 2022). "In the immune response to sepsis, the serum levels of PSEP do increase before the ones for procalcitonin or IL-6, so it has been proposed as a potential biomarker of infection and systemic inflammation, with proposed cut-off levels for sepsis of 400–600 pg/mL." (PMID 35054993, 2022). "In a prospective study including 68 newborns with early-onset sepsis (EOS) and 83 newborns as a control group, it was demonstrated that IL-6, TNF-α, HSP70, PCT, and CRP together with MMP-8 can be used as a predictive biomarker of EOS." (PMID 36613805, 2022). "The results in our work confirm that IL‐6, IL‐8, d‐dimer, and CRP are primarily the best indicators of identifying patients with sepsis." (PMID 36176597, 2022). "collected statistics of complete blood count, C-reactive protein (CRP), IL-6, levels of cell-free DNA (cfDNA), neutrophil elastase (NE) and myeloperoxidase (MPO) in umbilical cord blood to try to predict the early-onset sepsis." (PMID 35572571, 2022). "PCT and IL-6 had lower AUC’s than CRP in predicting sepsis but their sensitivity was higher – 87% for PCT and 86% for IL-6." (PMID 35550043, 2022). "ELISA showed that CLP-induced sepsis promoted the expression of inflammatory factors TNF-α, IL-1β, and IL-6." (PMID 35979014, 2022). "Compared with those in the sepsis group, the levels of IL-6, IL-1β and TNF-α were decreased (P < 0.05), the MDA content was decreased, with the SOD and CAT activities increasing in the sepsis + DMOG group (P < 0.05)." (PMID 35576220, 2022). "C-reactive protein (CRP), interleukin-6 (IL−6) and procalcitonin (PCT) have been widely used to facilitate sepsis diagnosis, with limited results." (PMID 36431277, 2022). "In the course of sepsis or ARDS, IL-6 plays a significant role, and its management can have a favorable influence on the condition." (PMID 36452899, 2022). "Sepsis induced an overexpression of the inflammatory mediators TNF-α, (p < 0.001) IL-6, (p < 0.001), IL-1β (p < 0.001) and IL-10 (p < 0.01)." (PMID 35795581, 2022). "In sepsis models, S1P3−/− mice had reduced survival rates concomitant with increased inflammatory response of TNF-α and IL-6." (PMID 35094654, 2022). "Sepsis is comprised of two phases, hyper-inflammatory phase featured by dramatic elevation of potent cytokines such as TNF-α and IL-6, and immunosuppression phase where inflammatory cytokines decrease significantly." (PMID 35167625, 2022). "Pharmacological inhibition of mitoNEET using mitoNEET ligand-1 (NL-1) decreased the levels of pro-inflammatory cytokines such as IL-1β, IL-6, and TNF-α in animal models of sepsis, as well as LPS-induced inflammatory responses by macrophages in vitro." (PMID 35136051, 2022).